AR (androgen receptor)
Diseases named in the same sentence as AR in open-access papers (continued):
Sharing a sentence is not in itself a finding about the gene and the disease.
tumor (continued). "In stark contrast to the well-characterized pro-proliferative role of epithelial AR, stromal AR is less well understood and appears to exert tumor-suppressive functions." (PMID 41327318, 2025). "ORIC-944 demonstrated tumor growth inhibition in AR-positive, AR-mutant, AR-v7, ADT-responsive and ADT-resistant in vivo PCa models." (PMID 40805121, 2025). "Collectively, our findings demonstrate that SCORT‐CasRx‐pre‐gHoxB13 treatment decreases metastatic tumor growth and angiogenesis while promoting apoptosis of both AR+ and AR‐ CRPC." (PMID 40349174, 2025). "It has been found that a specific antibody targeting Notch1 (OMP-A2G1) can inhibit tumor growth by affecting DNA damage repair and AR expression in a mouse model of PCa." (PMID 39711287, 2025). "Among SDC, 81.1% were androgen receptor (AR)-positive, and 54.5% showed nuclear AR positivity in > 70% of tumor cells (ARhigh), whereas 45.5% showed nuclear AR positivity in ≤ 70% of tumor cells (ARlow)." (PMID 41083996, 2025). "UMAP analysis of the snATAC-seq data revealed 4 tumor cell clusters with distinct open chromatin patterns in AR (ARPC) and COL1A2 (SARC)." (PMID 40493417, 2025). "The interaction between AR signaling and the tumor microenvironment is highly complex, exhibiting both oncogenic and tumor-suppressive influences." (PMID 40959108, 2025). "This suggests a differential role for NKX3.1, perhaps during tumor initiation or early stages of disease versus the dependency on expression when AR activity is high in late stages and in castration-resistant disease." (PMID 39858088, 2025). "Non-coding RNAs also indirectly influence the activity of AR signaling in the tumor microenvironment by regulating immune cell infiltration and inflammatory responses, further promoting tumor progression and resistance." (PMID 40008000, 2025). "Both Inhibitor of Growth factors, ING1 and ING2, belonging to a family of type II tumor suppressors are interacting partners of the AR and mediate cellular senescence." (PMID 41264145, 2025). "We also find that the tumor suppressive effects of AR inhibition are maximized under conditions that require OXPHOS for cellular energetics, including when cells are forced to utilize mitochondrial metabolism of ketones for ATP synthesis." (PMID 41216931, 2025). "The androgen receptor (AR) plays a central role in the initiation and progression of PCa, promoting tumor cell proliferation and survival through androgen-dependent signaling." (PMID 41514539, 2025). "This phenomenon has been recognized as a major driver of resistance to the androgen receptor (AR)-targeted therapies, such as enzalutamide and abiraterone, which are designed to block AR signaling and inhibit tumor growth." (PMID 40722714, 2025). "In recent years, with the deepening understanding of tumor biology and targeted therapies, the androgen receptor (AR) has attracted considerable attention." (PMID 40583627, 2025). "The relationship between circulating androgen levels and tumor-intrinsic AR activity is quite complex." (PMID 41228208, 2025). "The androgen receptor (AR) signaling pathway drives tumor growth and progression by regulating essential transcriptional programs for proliferation and survival." (PMID 41375053, 2025). "In summary, short-term effects of ADT were observed on tumor cell nuclear AR levels and apoptosis, as well as on stromal POSTN and PDGFRB levels." (PMID 40841830, 2025). "AR is a central driver of PCa initiation and progression and remains a critical pathway sustaining tumor growth in CRPC." (PMID 41514658, 2025). "Deregulated AR and ER signaling contributes to tumor growth and complexity, making these pathways key targets for developing more effective therapies against these cancers." (PMID 41155227, 2025). "In PCa, where androgen-receptor (AR) signaling is a dominant driver, AR has been reported to crosstalk with inflammatory/interferon pathways and to influence tumor–immune interactions." (PMID 41573646, 2025).
tumor (continued). "This is seen most dramatically in the P1 model that exhibits the highest H-score for AR expression where testosterone therapy of an established tumor extended the life span by as much as almost one year." (PMID 40002188, 2025). "Multivariate Cox analysis suggested that a smaller tumor size, lower nodal status, and AR expression were independent predictors of longer survival rates in TNBC patients." (PMID 40150035, 2025). "The main exceptions pertain to androgen receptor signaling and disease burden, and, to a smaller extent, to certain tumor suppressor genes." (PMID 40805181, 2025). "Higher AR expression was also correlated with male patients, lower tumor grade, and early stages of RCC." (PMID 41228208, 2025). "Elevated c-Myc promotes tumor growth through global induction of transcription as well as regulation of androgen receptor." (PMID 40044981, 2025). "Firstly, non-coding RNAs can directly bind to AR or regulate its downstream target genes, thereby affecting tumor cell proliferation, invasion, and resistance." (PMID 40008000, 2025). "While the AR has been investigated in multiple tumor types, its role in adult-type diffuse gliomas remains largely unexplored." (PMID 41153666, 2025). "Recent advancements in tumor immunotherapy, including androgen deprivation therapy (ADT), have rekindled interest in the effects of androgens and AR signaling on T cell-mediated tumor immunity." (PMID 40303343, 2025). "It is vital to note that AR activity is necessary for tumor development and is the primary driver of disease progression to the castration-resistant phase during ADT." (PMID 40510029, 2025). "All 6 (100%) cases of CCCA were negative for ER and PR staining whereas one (17%) had expressed AR in which 20% of the tumor cells showed 2 + positivity." (PMID 40392873, 2025). "The potential interaction of AURKA with the AR pathway provided the complexity of tumor progression and drug resistance." (PMID 40718709, 2025). "SMYD2 plays a crucial role in tumor progression and therapeutic resistance through its involvement in AR signaling, tumor aggressiveness, and metastasis." (PMID 41470892, 2025). "Nascent PCa harbors distinct HER2-high and AR activity–high subpopulations of tumor cells that are differentially responsive to HER2 inhibition." (PMID 40906535, 2025). "By disrupting HSF1 activity, NXP800 induces an unfolded protein response, leading to proteotoxic stress, suppression of AR activity, and ultimately, inhibition of tumor growth." (PMID 41235005, 2025). "In PCa, AR signaling supports tumor growth and survival, while PI3K/AKT activation, due to PTEN loss, drives proliferation and resistance to AR-targeted therapies." (PMID 40361412, 2025). "Of particular note, SPOP exerts tumor-suppressive effects by inducing the ubiquitination and degradation of oncoproteins, including c-Myc, androgen receptor (AR), and estrogen receptor-α (ERα)." (PMID 40483310, 2025). "In PC, oxidative stress has been linked to tumor initiation and progression, as well as to the development of CRPC, in part through activation of AR signaling pathways." (PMID 40868127, 2025). "Positive AR expression in male RCC patients has been linked with lower pathological grade and earlier tumor stage." (PMID 41034844, 2025). "This contrasts with primary tumor tissue, where reduced AR staining is accompanied with a clear reduction in tumor cell proliferation and moderately increased apoptosis during the first weeks after surgical castration." (PMID 40841830, 2025). "Further studies in animal models are needed to validate the effects of targeting PCNA/AR interaction on tumor growth, and cyclin A2 and AR expression in tumor lesions." (PMID 40391771, 2025). "In this context, the combination of atezolizumab and androgen receptor pathway inhibitors (ARPIs, agents that block androgen receptor signaling to suppress tumor growth) in mCRPC has been evaluated with mixed results." (PMID 40227610, 2025).
tumor (continued). "Another study also revealed that AR inhibited the activity and stemness of male tumor-infiltrating CD8+ T cells by regulating epigenetic and transcriptional differentiation programs." (PMID 41262256, 2025). "Such alterations enable tumour cells to sustain AR-driven transcription despite androgen depletion, underpinning resistance to standard AR-targeted therapies." (PMID 41374958, 2025). "As AR signalling continues to drive tumour growth in this setting, new therapeutic strategies are being developed to disrupt the AR axis through both direct and indirect mechanisms." (PMID 41374958, 2025). "This not only blocks lipid metabolism, which is required for tumor development, but also induces apoptosis and limits PCa cell growth by suppressing AR expression and activity." (PMID 41009695, 2025). "Available data suggest that ERG and AR collaborate to drive PCa development, with ERG modulating the AR transcriptional program and facilitating the expression of AR target genes that enhance tumour growth and survival." (PMID 40165885, 2025). "In hormone receptor-positive BCs, estrogen receptor alpha (ERα) and androgen receptor (AR) bind to specific enhancer regions, activating transcriptional programs that promote tumor growth and survival." (PMID 41011238, 2025). "In ER-positive breast cancer, AR functions as a tumor suppressor by inhibiting cell proliferation and interfering with ER signaling via competitive binding to the estrogen response element—a concept supported by a meta-analysis." (PMID 39851328, 2025). "Those ARBS with canonical AREs are proposed to have tumor suppressing activity in healthy prostate tissue while composite motifs containing both AR:FOXA1 motifs are enriched in primary PCa ARBS." (PMID 40833121, 2025). "AR switches from tumor suppressive to tumor promoting during prostate carcinogenesis, and AR is still the driving oncogene in the majority of late-stage PCa." (PMID 39858088, 2025). "In mice bearing LNCaP xenograft tumors, curcumin administration significantly slowed tumor growth and was shown to suppress tumor AR expression and PSA production in vivo." (PMID 41020902, 2025). "The study revealed that the stemness maintenance capacity of tumor-infiltrating CD8+ T cells governs sexual dimorphism in tumor immunity, while intrinsic androgen receptor (AR) signaling significantly suppresses the properties of stem-like CD8+ T cell subsets." (PMID 40894073, 2025). "The p66Shc expression in PCa is often upregulated in response to androgens, the primary hormones driving PCa growth, through androgen receptor (AR) signalling pathways, and creates a microenvironment conducive to tumour growth." (PMID 40690563, 2025). "Cheng and colleagues discovered in 2020 that the transcription factor Interferon Regulatory Factor 1 (IRF1) acts as a tumor suppressor in an AR-mediated transcriptional regulatory network in PC." (PMID 40001606, 2025). "Several trials showed that adding androgen receptor pathway inhibitors (ARPIs), a class of drug that inhibits tumor growth by blocking androgen receptor pathways, to ADT can also improve OS." (PMID 40899400, 2025). "Compensatory ER signaling triggered by AR-targeted therapies remodels tumor evolution and microenvironment adaptation via ERα/ERβ imbalance." (PMID 40519259, 2025). "At diagnosis, PCa is typically androgen-driven, relying on ligand-mediated signaling through the androgen receptor (AR) to support tumor growth and progression." (PMID 40361461, 2025). "While the role of AR in initial tumorigenesis can be either oncogenic or tumor suppressive, in established cancer cells, AR generally stimulates cell proliferation and promotes tumor growth." (PMID 41228208, 2025). "AR plays a role in almost all aspects of cancer development, such as tumor cell proliferation, apoptosis, invasion, metastasis, tumor microenvironment modulation, tumor immune responses, drug resistance, and patient survival." (PMID 41228208, 2025).
tumor (continued). "MiRNAs, key post-transcriptional regulators, contribute to PC via dysregulated biogenesis and modulation of androgen receptor signaling within an inflamed, remodeled tumor microenvironment." (PMID 41048023, 2025). "Expression of the FOLH1 gene, which encodes PSMA, is dynamically regulated by androgen receptor (AR) signaling—it is upregulated by androgen deprivation but downregulated after prolonged AR pathway inhibition or in AR-independent tumor evolution." (PMID 41374949, 2025). "Specifically, bile acids bind to and inhibit the AR, thereby modulating tumor cell growth signaling pathways and activating immune cells to enhance anti-tumor immunity." (PMID 41050671, 2025). "It arises due to adaptive resistance mechanisms, including androgen receptor (AR) pathway alterations and leads to changes in tumor biology and heterogeneity." (PMID 40464929, 2025). "CBP and p300 are key chromatin coactivators and histone acetyltransferases that play a critical role in CRPC by enhancing AR signaling and promoting tumor growth." (PMID 41235005, 2025). "Conversely, AR can also promote tumor progression by inducing the expression of metalloproteinases, thus facilitating extracellular matrix degradation, and enhancing tumor cells’ migration and invasiveness." (PMID 40150035, 2025). "Accordingly, concurrent anti-AR therapy, apart from its direct anti-tumor activity, was anticipated to enhance the efficacy of conventional therapy in patients with urothelial cancer." (PMID 40486871, 2025). "While these AR-centric mechanisms have been extensively explored, the influence of tumor microenvironmental factors, especially hypoxia, has received comparatively less attention." (PMID 40643528, 2025). "All 13 patients (100%) with AR alterations experienced tumor progression and demonstrated resistance to ongoing or prior ARSi therapy." (PMID 40558023, 2025). "Genetic instability, chromosomal aberration, remodeling of the tumor microenvironment, alterations in androgen receptor (AR) signaling, dysregulation of additional genes and DNA damage response (DDR) are considered to constitute a complex pathogenesis of CRPC." (PMID 41200193, 2025). "Nevertheless, other mechanisms (e.g., AR-independent bypass pathways, tumor stem cells) have also been advocated to explain progression to androgen independence." (PMID 40141159, 2025). "Consistent with the gut–barrier–tumor axis, the Akkermansia metabolite inosine preserves epithelial integrity, lowers circulating LPS, and down-modulates tumor NF-κB/AR signaling to delay castration resistance." (PMID 41339918, 2025). "Continued tumor progression despite serum testosterone levels below 50 ng/dL suggests that tumor cells can activate androgen receptor (AR) signaling pathways via alternative mechanisms." (PMID 41010740, 2025). "ALDH1A1 promotes tumor progression by enhancing the transcriptional activity of both the androgen receptor (AR) and the retinoic acid receptor (RAR), whereas ALDH1A3 appears to exert inhibitory effects." (PMID 40708788, 2025). "Preclinical studies suggest that AR inhibition can reprogram the immunosuppressive tumor microenvironment, enhancing T cell cytotoxicity and potentiating ICI efficacy." (PMID 41383624, 2025). "These therapies work by blocking AR signaling, leading to decreased tumor growth and increased sensitivity to other treatments." (PMID 40286049, 2025). "Ninety percent of SDC cases show androgen receptor expression, making the tumor a potential target for androgen deprivation therapy." (PMID 41357819, 2025). "Evidence suggests that androgen receptor antagonists improve tumor control in mouse models of bladder cancer 175-177." (PMID 40303343, 2025).
tumor (continued). "The overexpression of this isoform suppressed tumor growth in LAPC4 xenografts in castrated mice, whereas its knockdown enhanced AR signaling and promoted tumor growth in 22Rv1 xenografts." (PMID 40647540, 2025). "From mechanistic studies in cell lines and animal models to biomarker validation in patient cohorts, evidence supports the idea that AR–ncRNA axes govern tumor growth, invasion, immune evasion, and treatment response." (PMID 40806474, 2025). "Studies have shown that compared to hormone-sensitive prostate cancer, AR expression is notably upregulated in CRPC tissues, and this change is closely associated with enhanced proliferation capacity of tumor cells and treatment resistance." (PMID 40008000, 2025). "The fusion of TMPRSS2 and ETS genes, particularly involving ERG, regulates the AR pathway and impairs tumor proliferation checkpoints." (PMID 40746562, 2025). "Multiple mechanisms promote tumor recurrence by restoring AR signaling or bypassing AR dependence, allowing PCa growth." (PMID 41154598, 2025). "Consistent with its role in inhibiting multiple tumor cellular phenotypes, SCORT‐CasRx‐pre‐gHoxB13 treatment downregulates several oncogenic pathways and upregulates multiple tumor suppressive gene pathways in AR+ CRPC tumors." (PMID 40349174, 2025). "In summary, these findings demonstrated the potent anti‐tumor effects of L14‐8 by inducing ferroptosis, either combined with ARSIs in the AR‐positive cancer types or alone in the AR‐negative cancers, such as NEPC." (PMID 40536697, 2025). "Although the role of AR in ER+ BC is context-dependent, our results demonstrate that AR promotes tumor cell survival in the context of AI-resistant ER-mutant BC." (PMID 41216931, 2025). "By inducing an immune response against AR-expressing cells, pTVG-AR with GM-CSF aims to combat tumor growth even in the context of hormone therapy resistance." (PMID 39833784, 2025). "Currently, one of the primary therapeutic strategies for CRPC involves tumor suppression by targeting the AR, with enzalutamide being a prominent example." (PMID 40771930, 2025). "There were no significant changes in PSA score or Ki67 levels among hormone-naïve, short-term treated, or CRPC patients; however, short-term treatment appeared to lower tumor epithelial AR levels and to increase apoptosis." (PMID 40841830, 2025). "Studies on SDC have demonstrated that the AR signaling pathway is involved in tumor progression and invasiveness." (PMID 40625920, 2025). "We noted that accompanying PPL tumor progression, there was a gradual decline in the expression of AR and the luminal marker CK8, alongside an increase in the expression of the basal marker P63." (PMID 39743630, 2025). "Testosterone has been shown to influence immune responses by modulating androgen receptor (AR) signaling, which affects various immune cells in the tumor microenvironment." (PMID 40438106, 2025). "In humans, higher AR expression in tumor-infiltrating CD8+ T cells correlates with T cell exhaustion, suggesting that sex-biased differences in T cell stemness contribute to cancer progression and responses to immunotherapy." (PMID 40438106, 2025). "Clinical evidence confirms that endocrine therapies for PRAD primarily focus on androgen axis disruption, where reactivated AR signaling drives therapeutic resistance and tumor advancement." (PMID 40656519, 2025). "Despite this clinical success, tumor cells can escape AR dependence by transitioning from AR-dependent luminal cells to AR-independent NEPC cells (lineage plasticity)." (PMID 41509338, 2025). "EGFR, ERBB2, and FGFR1 are known to promote tumor growth and survival independently of AR signaling." (PMID 40429793, 2025). "During prolonged ADT for PCa, strong selective pressure within a low-androgen environment favors the survival of tumor cell clones that maintain AR activity, ultimately leading to CRPC." (PMID 40427518, 2025).